GFAP (glial fibrillary acidic protein)
Diseases named in the same sentence as GFAP in open-access papers (continued):
Sharing a sentence is not in itself a finding about the gene and the disease.
tumor (continued). "Surprisingly, 77.8% (14/18) cases showed positive staining of the nuclei of tumor cells for TTF1 using the EP229 clone in embryonal, GFAP-negative tumor components only." (PMID 33876327, 2021). "The tumor cells were positive for synaptophysin and neuron specific enolase (ESN) immunostains, focal for glial fibrillary acidic protein (GFAP) and negative for epithelial membrane antigen (EMA)." (PMID 33964714, 2021). "Immunohistochemical staining for S100 protein was diffusely and intensely positive, whereas GFAP and EMA were negative in the tumor cells." (PMID 34407809, 2021). "The immunohistochemical reactions for glial fibrillary acidic protein (GFAP), synaptophysin, neuron-specific enolase (NSE), neurofilament (NF), pancytokeratin (AE1/3), beta-HCG, AFP, PLAP were negative in the tumor cells." (PMID 33230629, 2020). "Jung and colleagues demonstrated detectable GFAP values in 40 of 50 GBM patients’ serum samples (median: 0.18 μg/L; range: 0 to 5.6 μg/L) using ELISA test, when non-GBM tumor patients and all healthy subjects showed zero serum GFAP levels in all samples." (PMID 33227903, 2020). "PDGFRα was also highly coexpressed by the ASCL1+ and OLIG2+ (not shown) tumor cells, whereas GFAP and to a lesser extent S100β and NEUN, although found in some parts of the tumor, did not overlap significantly with SOX2 or ASCL1." (PMID 32573857, 2020). "As for the makers such as GFAP, Olig-2, and NSE, the negative findings indicated that different recurrence patterns do not result from the cell types from which the tumor origins." (PMID 33585189, 2020). "The results showed that the signals of GFAP and CAIX were co-localized at tumor edge, but not at tumor core." (PMID 31106146, 2019). "The tumor cells were positive for CD68, NSE, S-100, and CD163 expression but negative for GFAP, Syn, and CD123 expression." (PMID 31023279, 2019). "Glial fibrillary acidic protein (GFAP)+ Ki67− cells were detected, suggesting the presence of non-proliferative glial cells in tumor organoids, similar to parental tumor tissues (m’, S1j, j’ and S2j, j’)." (PMID 30353124, 2018). "Cells positive for Nestin, CD133, GFAP, BIIIT, SSEA4, and Olig2 had a tumor-dependent pattern of expression, which did not have a dichotomous association with grade." (PMID 29849507, 2018). "In contrast, 41% (7/17) of the [GFAP-tTA;TRE-SmoA1;AMPKα2−/−] mice survived beyond one year and do not show any evidence of tumor upon histological analysis." (PMID 30360486, 2018). "Densely organized neoplastic cells were negative for Glial fibrillary acidic protein (GFAP), vimentin and S-100, while isolated or small cluster tumor cells were intensely immunopositive for Neuron enolase (NSE), Neurofilament (NF), and cytokeratins." (PMID 29056700, 2017). "Late or absent tumor progression was accompanied by a persistent reduction in both CD9+/SVN+ and CD9+/GFAP+/SVN+ exosomes in 2 of 3 patients as well." (PMID 29383115, 2017). "Xenografted cells replicated the phenotype of the original tumour, displaying high expression of nestin, nf-200 and CD133, and no expression of CD15, CD44, GFAP." (PMID 28417956, 2017). "The tumor was positive for OLIG2 and GFAP and negative for BRAF V600E and IDH1 R132H mutant protein immunostains." (PMID 29141672, 2017). "No positivity was noted for neuron-specific enolase (NSE), glial fibrillary acidic protein (GFAP), epithelial membrane antigen (EMA), or actin in the tumor cells (data not shown)." (PMID 27248819, 2016). "The tumor was strongly immuno-reactive for GFAP, SMARCB/INI-1 was preserved, and the tumor was negative for chromogranin, synaptophysin, Cam 5.2, EMA, desmin, myogenin, neurofilament and mutant-specific IDH1 (R132H)." (PMID 27582545, 2016). "Otherwise, this tumor was positive for Cam5.2 and MAP-2 and negative for EMA, GFAP and synaptophysin." (PMID 27229317, 2016).
tumor (continued). "Under neural differentiation conditions, cells from sphere cultures of both UA and tumor core samples gave rise to cells that expressed markers of mature neurons and glial cells (MAP2, β-TubIII and GFAP), but not oligdendrocytes (O4)." (PMID 27605047, 2016). "Almost all tumor cells were positive for vimentin, partially positive for CD68, and negative for S100 protein, glial fibrillary acidic protein (GFAP), CD34, epithelial membrane antigen (EMA), and smooth muscle actin (SMA)." (PMID 25951848, 2015). "Immunohistochemistry results in our patient showed diffuse positivity for HMB-45 and S-100 protein and weak patchy cytoplasmic positivity for Melan A. Also tumor cells were negative for EMA and GFAP." (PMID 26294993, 2015). "In P22 cultures, 52 7% of cells were positive for SMA, while the GFAP (27 5%), beta-tubulin III (21 9%), and SOX2 (36 3%) positive cells are most likely human tumor cells as there was not a complete selection towards rat stromal cells." (PMID 24349039, 2013). "The tumour was strongly positive for CD31, factor VIII and cytokeratin MNF116 and negative for glial fibrillary acidic protein (GFAP), epithelial membrane antigen (EMA), Mart-1, and S-100 protein." (PMID 24171128, 2013). "The tumor tissues showed a positive reaction for CD117, CD34 and vimentin, but not for desmin, PLAP, S-100, SM-actin, NF, GFAP, NSE, HMB-45, and SC-actin." (PMID 19500398, 2009). "The tumor cells co-expressed CKAE1/3, EMA, and S100, while SOX10, GFAP, p63, and SMA were negative." (PMID 39636306, 2025). "LCL161 treatment significantly increased the expression of glial fibrillary acidic protein (GFAP), a major marker of reactive astrocytes, within the tumor border with no significant impact on expression distally, illustrating a greater tumor-local astrocyte involvement following SMC treatment." (PMID 39147758, 2024). "The tumor can show variable expression of cytokeratins, CD34, desmin, SMA, claudin 1, and muscle‐specific actin and is consistently negative for S100 protein, Kit, and GFAP." (PMID 36074249, 2023). "Most notably, the tumor was found to be negative for Brachyury, CD68, SRY-box transcription factor 10 (SOX10), HMB45, glial fibrillary acidic protein, oligodendrocyte transcription factor 2, anaplastic lymphoma kinase, desmin, CD117, synaptophysin, and neurofilament." (PMID 37598295, 2023). "In addition, sample-wise analysis showed that the expression of TREM1, rather than GFAP or P2RY12, significantly correlated with EMT score, indicating that macrophage M2 infiltration moderately correlated with enhanced tumor stemness." (PMID 34540693, 2021). "Interestingly, within the tumour bulk, all GFAP-positive cells were also GFP positive, suggesting that the majority of non-tumoral cells present inside the tumour were microglia and TAMs." (PMID 28524852, 2017). "In this case, the tumor cells were proven chromophobic by Pearse’s PAS stain, showing immunopositivity for PRL, chromogranin-A, and synaptophysin but no immunoreactivity to S-100 protein, vimentin, and GFAP." (PMID 26228535, 2015). "This tumor was classified as an undifferentiated myxoid sarcoma based on the lack of a glial proliferation, strong CD68 and vimentin immunolabeling in the majority of tumor cells and the absence of CD1a and GFAP immunolabeling." (PMID 24073000, 2013).
tumor (continued). "The immunohistochemical profile of the tumor was positive for S-100 protein, focally positive for epithelial membrane antigen (EMA) and weakly positive for synaptophysin at some locations and negative for pankeratins AE1/AE2, GFAP, HMB45 and MART-1." (PMID 23351137, 2013). "The tumor was pankeratin AE1/AE2, GFAP, HMB45 and MART-1/Melan-A negative." (PMID 23351137, 2013). "GFAP immunoreactivity was absent within the tumour masses for the CRCTU Walker 256 internal carotid artery model, indicating the absence of astrocytes within the tumours." (PMID 23374226, 2013). "The tumor cells were strongly positive for wide-spectrum cytokeratin, BerEP4, and alpha-fetoprotein (αFP); partially positive for CD117 (C-kit); negative for glial fibrillary acidic protein (GFAP), S-100 protein, CD30, and the beta subunit of human chorionic gonadotropin (βHCG)." (PMID 23326746, 2012). "The in situ hybridisations revealed mutually exclusive topographic distribution of myc and glial fibrillary acidic protein (GFAP) mRNAs, and a lack of correlation between myc expression and proliferative activity, max and RB1 mRNAs were detected in most tumours and cell lines." (PMID 8286200, 1994). "Both tumors express, consistent with their glial lineage, the glial fibrillary acidic protein (GFAP), whereas other markers are reported to have distinct immunoreactivity, e.g. the endothelial marker CD34 is frequently expressed in tumor cells of PXA, respectively not in tumor cells of gcGBM." (PMID 27253461, 2016). "The tumours that grew 9 days following internal carotid artery injection of CRCTU Walker 256 cells within the lateral ventricles had limited contact with the neuropil and lacked the GFAP positive astrocytic border that was evident around the ATCC Walker 256 tumour." (PMID 23374226, 2013). "However, no tumor was observed in this study when GFAP-IgG coexisted with NMDAR-IgG, which may be due to ethnic specificity, as tumors were rare in Chinese patients with anti-GFAP antibodies." (PMID 37205100, 2023).
infection (251 papers, 2007 to 2026). The state of being infected such as from the introduction of a foreign agent such as serum, vaccine, antigenic substance or organism. "Western blot analyses indicated infection-associated GFAP upregulation and IL-33 alterations across brain regions, whereas co-therapy shifted these markers toward uninfected levels in a region- and strain-specific manner." (PMID 41652430, 2026). "An increase in astroglia (as measured by GFAP) was also observed in CJD-infected organoids (GFAP), another hallmark sign of infection." (PMID 41048331, 2025). "As expected, the Tax protein was detected in 2% of the spinal cord astrocytes, and it was identified based on their expression of GFAP, confirming their susceptibility to the infection, as in human cases." (PMID 36802226, 2023). "GFAP immunopositivity revealed astrocytic hypertrophy in the context of aging, suggestive of astrocyte activation, however, this was more pronounced in infection, which also displayed significant loss of individual astrocytic domains." (PMID 35365631, 2022). "After A. cantonensis infection, the expression of GFAP in the brain of infected mice increased, indicating that the infection is able to cause damages to the central nervous system and activate astrocytes for repairing and regeneration." (PMID 33917604, 2021). "We thus detected the aberrant presence of GFAP-positive glial cells and the expression of genes associated with responses to infection in the mutant retina." (PMID 34664634, 2021). "When adjusted for sex and infection, worse Sarnat score was associated with higher tau and GFAP levels, more so after TH." (PMID 34795631, 2021). "Both viruses induced astrogliosis, with stronger GFAP activation in Nef-deficient infections." (PMID 39532531, 2025). "In response to pathogenic stimuli, ranging from injury, infection, to neurodegenerative disease, astrocytes enter a reactive state (reactive astrocytes) with a high level of glial fibrillary acidic protein (GFAP), a key component of astrocyte intermediate filaments." (PMID 40021824, 2025). "GFAP is an intracellular protein, and we hypothesize that it may be associated with astrocyte exposure to antigens resulting from pathogen infection, potentially leading to autoimmune reactions." (PMID 39720731, 2024). "Infection appears to be associated with the pathogenesis of GFAP astrocytopathy but the neuroimmune mechanism that infection activates is unknown." (PMID 37205100, 2023). "In the context of insult, pathogen infection, or neurological disease, astrocytes undergo functionally complex reactive responses that are associated with an increase in glial fibrillary acidic protein (GFAP) gene and protein expression." (PMID 36206386, 2022). "In our previous study, we found that HBCA were permissive to TBEV infection and that infection with the low-pathogenic TBEV strain Neudoerfl induced markedly increased expression of glial fibrillary acidic protein (GFAP), which is a marker of astrocyte activation." (PMID 31699097, 2019). "Interestingly, infection-associated decreases in GFAP expression were significantly attenuated in animals that received the NK-1R antagonist aprepitant." (PMID 28202084, 2017). "The astrocyte marker GFAP increased with infection in several brain regions but was decreased with cART treatment, suggestive of a protective effect of cART." (PMID 41165991, 2025). "In the context of EcoHIV infection, immunohistochemical analysis showed increased GFAP expression in the caudoputamen region in the vicinity of the injection at 2-wk post infection." (PMID 39532531, 2025). "Immunostaining on TFs revealed that both NERUOD1 and DLX2 were initially expressed in GFAP+ astrocytes at 10 days post infection." (PMID 40401537, 2025). "Given the previous studies, which have shown that GFAP serves as a marker for the activation of astrocytes, this result hinted that astrocytes can be activated after CV-A10 infection (white arrow)." (PMID 41165313, 2025).
infection (continued). "In contrast, PbA infection-induced ECM controls (Pb group) demonstrated a significant increase in GFAP+ (P < 0.01) and Serping1+ (P < 0.01) astrocytes compared with uninfected mice." (PMID 41214704, 2025). "In contrast, the cells infected with TFs were initially GFAP+ astrocytes at the early stage of 10 days post infection but gradually changed their cell fates into NEUN+ neurons." (PMID 40401537, 2025). "In previous studies, IHC analysis of EcoHIV-infected mice showed an increase in GFAP staining in the basal ganglia in the vicinity of the injection site at 2-wk post infection." (PMID 39532531, 2025). "We stained 9-month Infection and Therapy cohorts with astrocytic marker glial fibrillary acidic protein (GFAP) and microglial marker, Ionized Calcium Binding Adaptor Molecule 1 (Iba1)." (PMID 41430261, 2025). "Through western blot analysis, we observed that EV-A71 infection resulted in the upregulation of GFAP, C3, and C5aR1 expression in a time-dependent manner." (PMID 39679722, 2025). "Transfection specificity (ratio mCherry+/GFAP+ cells; 94.0%) and perturbance (ratio GFAP+/mCherry+ cells; 84.3%) was analyzed three weeks post-infection within the PVN." (PMID 39702695, 2025). "In order to ascertain the origin of the escalated complement C3 levels, we conducted staining of complement C3 with astroglia cell marker (GFAP) or microglia cell marker (Iba-1) at different time points following infection." (PMID 40294039, 2025). "The immunoreactivity of glial fibrillary acidic protein (GFAP) and S100β, markers of astrogliosis, were predominantly elevated in the hippocampal and internal capsule regions as the duration of infection increased." (PMID 40929057, 2025). "We observed that the plasma GFAP concentration in patients with severe infection was significantly greater than that in patients with mild infection, and this change seemed to occur on day 3 after onset." (PMID 39679722, 2025). "We classified the efficiency of infection by co-staining SARS-CoV-2 nucleocapsid (N) with GFAP or β-tubulin III." (PMID 41139159, 2025). "To investigate the relationship between PrPSc accumulation, gliosis, and TLR expression, we examined protein levels of GFAP and PrPSc in the cerebellum at 60, 90, 120, and 145 days post-infection (dpi)." (PMID 38698886, 2024). "Networks of GFAP+ EGCs in samples from untreated infections showed the weakest staining intensity and contained fragmented GFAP aggregates and patches in the plexus compared to controls, cured and relapsed mice." (PMID 38782898, 2024). "GFAP was significantly upregulated 5.4-fold by infection (log2FC 2.4), consistent with the GFAP IHC and reactive astrogliosis seen herein." (PMID 40295675, 2024). "We also found GFAP intensity was increased with acute infection in the putamen and hippocampus (p = 0.0112 and p = 0.0346, respectively)." (PMID 39149452, 2024). "Specifically, at 2-weeks post-infection HIV-1CH040 infected mice showed higher GFAP fluorescence in the frontal cortex and hippocampus compared to HIV-1CH040 infected mice analyzed at 8-weeks post-infection (p’s < 0.001)." (PMID 38945996, 2024). "Benznidazole treatment induced a doubling of GFAP protein abundance compared to controls and the disappearance of the secondary band, while the relapse infection group showed a more moderate increase overall and a minor secondary band." (PMID 38782898, 2024). "First, we measured the total numbers of astrocytes and apoptotic astrocytes (caspase-3+/GFAP+) at 5 and 9 days post-infection." (PMID 39339840, 2024). "The astrocyte marker GFAP increased with infection in several brain regions, but was broadly decreased with cART treatment, suggestive of a protective effect of cART." (PMID 39149452, 2024). "A common feature of astrocytes responding to injury, disease, or infection (reactive astrocytes) is the upregulation of GFAP." (PMID 38891941, 2024).